UQCC3 (ubiquinol-cytochrome c reductase complex assembly factor 3)
Description:
Required for the assembly of the ubiquinol-cytochrome c reductase complex (mitochondrial respiratory chain complex III or cytochrome b-c1 complex), mediating cytochrome b recruitment and probably stabilization within the complex. Thereby, plays an important role in ATP production by mitochondria. Cardiolipin-binding protein, it may also control the cardiolipin composition of mitochondria membranes and their morphology.
Synonyms: C11orf83; UNQ655; CCDS41658.1; MC3DN9
Tractability: Antibody: UniProt predicts a signal peptide or a membrane-spanning region. PROTAC: ubiquitination databases record sites on it.
Gene: Protein-coding gene on chromosome 11 (62,670,273 to 62,673,686, forward strand). Ensembl gene ENSG00000204922.
Subcellular location: Mitochondrion inner membrane
Subcellular location (Human Protein Atlas): Mitochondria; Nucleoplasm; Cytosol
Pathways (Reactome):
Metabolism: Complex III assembly
Gene Ontology:
Molecular function: cardiolipin binding; phosphatidic acid binding
Biological process: cristae formation; mitochondrial electron transport, ubiquinol to cytochrome c; mitochondrial respiratory chain complex III assembly
Cellular component: mitochondrial inner membrane; mitochondrion
Genetic constraint (gnomAD): Loss-of-function variants: 7 observed, 6.46 expected, observed/expected ratio (o/e) 1.08, 90% interval 0.61 to 1.81. That is too few expected variants to judge how well the gene tolerates losing a copy. Missense variants: 141 observed, 121.44 expected, observed/expected ratio (o/e) 1.16, 90% interval 1.01 to 1.34. Synonymous variants: 57 observed, 56.12 expected, observed/expected ratio (o/e) 1.02, 90% interval 0.82 to 1.27.
Gene-disease validity (ClinGen):
ClinGen rates the evidence that UQCC3 causes each of these diseases.
mitochondrial disease (autosomal recessive): Limited.
Homologues: Orthologues: chimpanzee UQCC3 (100% identical), dog UQCC3 (71% identical), pig UQCC3 (71% identical), rabbit UQCC3 (69% identical), guinea pig UQCC3 (60% identical), mouse Uqcc3 (56% identical), rat Uqcc3 (56% identical), rat LOC120093241 (55% identical).
Diseases named in the same sentence as UQCC3 in open-access papers:
UQCC3 is named in the same sentence as 3 diseases in open-access papers, as found by Europe PMC text mining. Sharing a sentence is not in itself a finding about the gene and the disease. The quoted sentences say what the papers report.
mitochondrial disease (1 paper, 2024). "Gene ontology analysis identified increased expression of genes involved in synaptic transmission and organization in FRDA and Ingenuity Pathway Analysis (IPA) displayed dysregulation of ubiquinol cytochrome C (UQCC3) associated mitochondrial disease pathways." (PMID 38420191, 2024).
UQCC3 also shares sentences with these, for which no sentence is quoted: schizophrenia (1 paper); viral infection (1).